SERPINA3 (serpin family A member 3)
Diseases named in the same sentence as SERPINA3 in open-access papers (continued):
Sharing a sentence is not in itself a finding about the gene and the disease.
psychiatric disorder (3 papers, 2020 to 2022). A disorder characterized by behavioral and/or psychological abnormalities, often accompanied by physical symptoms. "However, regardless of prolonged antipsychotic treatment, we identified both a subgroup of cases with psychiatric disorders who displayed elevated inflammation and positive correlations between both IL1B and SERPINA3 mRNAs and lifetime antipsychotic dose." (PMID 34911938, 2021).
benign tumors (1 paper, 2022). "SERPINA3 is commonly associated with the transition of benign tumors to invasive melanoma." (PMID 35884426, 2022).
immune system diseases (1 paper, 2022). "Serpina3 has been detected as a marker of ER stress in astrocytes in immune system diseases, and the role played by its Serpina3n (a protein from the same family) in ER stress has never been described." (PMID 36704356, 2022).
SERPINA3 also shares sentences with these, for which no sentence is quoted: Parkinson disease (5 papers); coronary artery disease (4); acute myocardial infarction (3); bipolar disorder (3); chronic kidney disease (3); malaria (3); metabolic disorders (3); prediabetes (3); Abdominal obesity (2); brain disease (2); breast tumors (2); Cirrhosis (2); cystic fibrosis (2); diabetic nephropathy (2); gastric cancer (2); infectious disease (2); intestinal tumors (2); lung fibrosis (2); metastatic melanoma (2); non-small cell lung carcinoma (2); schizoaffective disorder (2); acne (1); acute coronary syndrome (1); age-related macular degeneration (1); ANCA associated vasculitis (1); anemia (1); anencephaly (1); angina (1); Anxiety (1); autism spectrum disorder (1).
A further 55 diseases each share a sentence with SERPINA3 in 1 paper.